MDM2 (MDM2 proto-oncogene)
Diseases named in the same sentence as MDM2 in open-access papers (continued):
Sharing a sentence is not in itself a finding about the gene and the disease.
cancer (continued). "Qin X., Peng Q., Tang W., Lao X., Chen Zh., Lai H., Deng Y., Mo C.,Sui J., Wu J., Zhai L., Yang Sh., Li Sh., Zhao J. An updated metaanalysison the association of MDM2 SNP309 polymorphism withcolorectal cancer risk." (PMID 33959694, 2020). "While, separately MDM2 rs2279744 variant allele was reported to modify the MDM2 protein function also being reported by several studies as a risk factor for cancer." (PMID 32492903, 2020). "The present findings showed a significant association between the MDM2 40bp indel polymorphism and overall cancer risk as well as gastrointestinal cancer susceptibility." (PMID 31528638, 2019). "Subgroup analysis by cancer types proposed that MDM2 40bp indel polymorphism increased the risk of gastrointestinal cancer in heterozygous codominant, and dominant genetic models." (PMID 31528638, 2019). "This meta-analysis aimed to provide an up-to-date comprehensive evaluation on the association between the MDM2 40bp indel polymorphism and cancer susceptibility." (PMID 31528638, 2019). "Despite the limitations, our meta-analysis suggest that MDM2 40bp indel polymorphism is a risk factor for developing overall cancer as well as gastrointestinal cancer." (PMID 31528638, 2019). "In the present study we conducted an updated meta-analysis to find out the correlation between the 40bp indel polymorphism of MDM2 and cancer risk." (PMID 31528638, 2019). "Fourteen independent article including 13,562 cancer cases and 23,474 controls investigating the genetic effects of MDM2 40bp indel polymorphism on cancer risk were pooled in this analysis." (PMID 31528638, 2019). "It has been shown that the G-allele of SNP309 increased the affinity of the transcription factor Sp1 to the MDM2 P2 promoter, leading to elevated MDM2 expression and increased cancer risk." (PMID 30956778, 2019). "Several studies examined the impact of MDM2 40bp indel polymorphism and the risk of various cancers, but the findings were inconsistent and controversial." (PMID 31528638, 2019).
cancer (continued). "TP73 gene is rarely mutated in cancers and p73 protein is often inactivated by binding to oncogenic partners including MDM2, MDM4, ΔNp73, or mutant p5323." (PMID 30886745, 2019). "In our meta-analysis, 5 genetic models were considered including homozygote codominant, heterozygous codominant, dominant, recessive, and allele to evaluate the impact of MDM2 40bp indel polymorphism on cancer risk." (PMID 31528638, 2019). "MDM2 is an oncogene, the amplification and overexpression of which are linked to progression and poor prognosis of different cancers." (PMID 30271790, 2018). "MDM2 downregulation is necessary for CDK4/6 inhibitor therapy-induced senescence in a variety of cancer cell lines, and the loss of MDM2 is observed post palbociclib treatment in patients with WD/DDLS who have prolonged periods of PFS." (PMID 29789718, 2018). "Only one compound, Nutlin‐3a, an MDM2 inhibitor, was significantly sensitive in 18 cancer cells with CTNNB1 mutation." (PMID 29532999, 2018). "Study’s also demonstated that interaction of XIAP and MDM2 inhibit the ability of MDM2 as self-association and self-ubiquitination, which upregulate the MDM2 protein stabilization and cancer cell surivival." (PMID 29464049, 2018). "For example, a 40 bp indel variant residing in the mouse double minute 2 homolog (MDM2) gene promoter is in complete LD with a SNP (rs2279744), and the SNP locus has been demonstrated to be associated with the susceptibility to several cancers." (PMID 29616081, 2018). "The molecular mechanisms underlying the effects that MDM2-rs2279744 and MDM2rs937283 genetic variations have on cancer development and progression remain elusive." (PMID 28045062, 2017). "Several SNPs were identified in MDM2 genes, including 309 T > G in the MDM2 promoter sequence, resulting in increased expression and associated with dramatic increase in cancer incident and time of onset." (PMID 29137250, 2017). "In this review, Mdm2 can be overexpressed due to gene amplification or polymorphisms that increase promoter activation in many cancers activation." (PMID 29065514, 2017).
cancer (continued). "Up-regulation of MDM2 protein in cancer cells is caused by MDM2 gene amplification, elevated transcription, increased stability of MDM2 mRNA, enhanced translation and through misregulated posttranslational modifications." (PMID 29137250, 2017). "Along with overexpression of MDM2, several MDM2 splice variants or isoforms can be overexpressed in various human cancers and normal tissues." (PMID 29065514, 2017). "This region contains many oncogenes such as CREB3L4 and MDM2 and increase in their copy number has been linked with worse survival for many human cancers." (PMID 28969054, 2017). "The MDM2 promoter region contains several polymorphisms, some of which have been associated with MDM2 expression, cancer risk and age at cancer onset." (PMID 27081698, 2016). "IPA at 4 h revealed that 7 genes [Btg2, Ccng2, Cdkn1a, Gadd45b, Gadd45g, Phlda3, and Mdm2] of 18 genes, which showed statistically significant increases, were associated with cancer, cell cycle, cell death and survival, and cellular growth and proliferation." (PMID 27482301, 2016). "Herein, we evaluate the expression of MDM2, both the full length and a splicing variant MDM2-A, and the sensitivity of Nutlin-3 in different cancer cell lines." (PMID 27129163, 2016). "The oncogene, mouse double minute 2 (MDM2), has been implicated in the pathogenesis of numerous cancers." (PMID 27184007, 2016). "Two functional SNPs (SNP285G > C; rs117039649 and SNP309T > G; rs2279744) have previously been reported to modulate Sp1 transcription factor binding to the promoter of the proto-oncogene MDM2, and to influence cancer risk." (PMID 27624283, 2016). "The effect of single nucleotide polymorphisms (SNPs) at MDM2 has been investigated in several cancer types." (PMID 27506496, 2016). "Despite some limitations, this meta-analysis indicated that the MDM2 SNP285 polymorphism was associated with a decreased cancer risk, which warrants further validation in large and well-designed studies." (PMID 27890964, 2016). "In this meta-analysis, which included 16 published studies of 14,573 cases and 9,115 controls, we found that MDM2 SNP285 polymorphism was significantly associated with a decreased overall cancer risk in the heterozygous model." (PMID 27890964, 2016). "The genetic polymorphism rs2279744 (c.309T>G) of the MDM2 gene is reportedly associated with susceptibility and/or prognosis in various cancers." (PMID 27228500, 2016).
cancer (continued). "Given that germline cancer risk factors often are linked to a younger age at diagnosis, we compared mean age at diagnosis for individuals carrying the different MDM2 SNP55 genotypes within each diagnostic group." (PMID 27624283, 2016). "Taken together, these data indicate that the effect on cancer risk of the germline variations in the MDM2 promoter regions, in general, are more dependent on tissue type than on gender." (PMID 27081698, 2016). "MDM2 therefore appears to be a pivotal target in cancer therapy, particularly for the high-risk, refractory cancers." (PMID 27004407, 2016). "In summary, this meta-analysis suggests that MDM2 SNP285 polymorphism was significantly associated with a decreased overall cancer risk with the heterozygous model." (PMID 27890964, 2016). "This is important because MDM2-ALT1, the alternative splice variant of MDM2 that is predominantly generated in response to DNA damage, is also strongly associated with several cancer types." (PMID 25845590, 2015). "MDM2 overexpression in various cancer cell lines causes p14ARF reduction inducing its degradation through the proteasome." (PMID 25723571, 2015). "We found that binding of XIAP IRES to the MDM2 RING domain protein inhibited its ability for self-association and self-ubiquitination, which increased MDM2 protein stabilization and cancer cell survival." (PMID 25888903, 2015). "In cancer patients, MDM2 overexpression is associated with disease progression and poor treatment outcome." (PMID 25888903, 2015). "Recent studies have reported that MDM2 expression in malignant tumors is associated with invasion, metastasis, poor prognosis and chemotherapy resistance." (PMID 25435943, 2015). "An increase in mdm2 splice variants and protein isoforms are a common occurrence in cancer cells with MDM2 overexpression (see reviews)." (PMID 26416444, 2015). "In some cancers, high levels of MDM2 expression occur due to a single nucleotide polymorphism (snp) in the MDM2 gene promoter." (PMID 25888903, 2015). "MDM2 is also a substrate for alternative splicing and the production of aberrantly spliced MDM2 RNA is associated with a shortened overall survival of cancer patients." (PMID 25806049, 2015).
cancer (continued). "For a long time, many investigators have attempted to reveal an association between MDM2-overexpression, amplification, or genetic variation and increased cancer risk." (PMID 26293665, 2015). "MDM2 overexpression in cancers is associated with mdm2 genomic amplification, increased transcription and enhanced translation." (PMID 26416444, 2015). "Ethnic variation regarding distribution of SNP285C needs to be taken into account when assessing the impact of MDM2 SNPs on cancer risk." (PMID 25327560, 2014). "While multiple SNPs have been detected throughout the MDM2 promoters, effects on transcription and pathophysiological effects, such as associations with cancer risk, have been described for a few only." (PMID 25327560, 2014). "The status of this cancer risk reducing SNP needs to be taken into account when assessing the impact of other MDM2 SNPs on cancer risk across different ethnic and geographic populations." (PMID 25327560, 2014). "The MDM2 regulation of disorders is associated with the development of cancer, which is confirmed by the evidence that MDM2 was over-expressed in some human cancers." (PMID 25075210, 2014). "MDM2 single nucleotide polymorphism SNP (rs2279744) has already been described as being associated with several types of cancer, and also with accelerated tumorigenesis and poor prognosis." (PMID 25075210, 2014). "The over-expression of MDM2 due to a single nucleotide polymorphism of thymine to guanine (T to G) at position 309 of the MDM2 gene (mdm2 SNP309) is associated with increased cancer incidence and aggressiveness." (PMID 24147044, 2013). "Previous study showed that MDM2 polymorphism (rs2279744) located in the first intron of the MDM2 promoter was an independent prognostic factor for cancer patients." (PMID 24340057, 2013).